KRAS (KRas proto-oncogene, GTPase)
Diseases named in the same sentence as KRAS in open-access papers (continued):
Sharing a sentence is not in itself a finding about the gene and the disease.
pancreatic cancer (continued). "IKKε is reported to be important in KRAS-positive pancreatic models, in which oncogenic KRAS drives disease similar to human pancreatic cancer." (PMID 30223576, 2018). "A recently completed phase 1 trial delivered KRAS siRNA intratumorally in combination with chemotherapy in advanced pancreatic cancer." (PMID 29879129, 2018). "Knockdown of SMYD3 by RNAi has been reported to result in decreased cell proliferation in hepatocellular carcinoma, breast, cervical and esophageal cell lines and also in oncogenic KRAS -driven pancreatic cancer and lung adenocarcinoma cell lines." (PMID 29856759, 2018). "Mechanistically, the silencing of NEK9 led to decreased phosphorylation of its downstream substrate CHK1 in WM1366 melanoma cells as well as the MIA PaCa‐2 KRAS‐mutant pancreatic cancer cell lines." (PMID 29112787, 2018). "In the present study, we combined CRE/Lox and GAL4/UAS systems to establish the first KRAS-initiated pancreatic cancer model in zebrafish that highly recapitulates human PanIN development." (PMID 30533257, 2018). "In pancreatic cancer, KRAS upregulates GLUT1 (glucose transporter 1), as well as HK1 (hexokinase 1), HK2 (hexokinase 2), PFK1 (phosphofructokinase 1) and LDHA (lactate dehydrogenase A), which are key enzymes for the glycolytic processes." (PMID 31225458, 2018). "This strategy induced a KRAS-initiated pancreatic cancer model in zebrafish as evidenced by the development of the whole spectrum of PanIN." (PMID 30533257, 2018). "Although KARS inhibition should be an effective strategy to treat pancreatic cancer, the rapid recurrence of primary and metastatic cancer following reactivation of KRAS supports the existence of dormant cancer cells in the animal model." (PMID 30060755, 2018). "Together, our data suggest that matrine can suppress the growth of KRAS‐mutant pancreatic cancer by inhibiting autophagy‐mediated energy metabolism." (PMID 29791786, 2018). "With IACS-010759, KRAS-negative pancreatic cancer cells were selectively targeted since their glycolysis remained low, while KRAS-positive cells adapted by upregulating glycolysis as a compensatory mechanism." (PMID 29861847, 2018). "Among these signaling pathways activating PSCs, SHH expression in pancreatic cancer cells is induced by KRAS by the activation of nuclear factor-κB (NFκB)." (PMID 30060755, 2018). "Interestingly, a study has described how a mutation to the KRAS gene in pancreatic cancer cells display elevated levels of macropinocytosis, a form of endocytosis, of proteins such as albumin, a fact which may be behind the recent success of Abraxane in treating advanced pancreatic cancer." (PMID 29360800, 2018). "Cellular studies show the effectively reduced accumulation of activated KRas-GTP level in mutant KRas-driven pancreatic cancer cells, with concomitant attenuation of MEK and ERK activation." (PMID 29467941, 2018). "In vivo models modified by an inducible KRAS extinction mechanism in pancreatic tumors corroborate these findings." (PMID 30631752, 2018). "We therefore wanted to determine the effect of KSR1 deletion in a well-characterized mouse model of KRAS-driven pancreatic cancer." (PMID 29596465, 2018). "Others found that autophagy markers LC3 and p62 were elevated in a KRAS-positive pancreatic cancer model where TBK1 was deleted." (PMID 30223576, 2018). "Lastly, antisense oligonucleotides to KSR1 are able to reduce tumor growth of KRAS-dependent human pancreatic carcinoma xenografts in nude mice." (PMID 29596465, 2018). "Decreased RB phosphorylation and increased p27 expression were also observed in other NRAS‐mutant melanoma and KRAS‐mutant pancreatic carcinoma cells." (PMID 29112787, 2018).
pancreatic cancer (continued). "We aimed to uncover transcription factors that regulate the transcriptional response of oncogenic KRAS in pancreatic cancer and to understand their clinical relevance." (PMID 28141826, 2017). "In this way, targeting ER stress resistance in combination with ER stress-inducing drugs, like IPI-504 40 or bortezomib, represents a promising preventive or therapeutic strategy against aggressive KRAS-driven tumours like pancreatic cancer." (PMID 27941872, 2017). "In this study, the authors show that lung and pancreatic cancers expressing oncogenic KRAS can be targeted by genetic inhibition of FOSL1, which involves downregulation of genes of the mitotic machinery." (PMID 28220783, 2017). "High FOSL1 expression identifies mutant KRAS lung and pancreatic cancer patients with the worst survival outcome." (PMID 28220783, 2017). "The proto-oncogene c-MET, a bona fide therapeutic target in human malignancies, including pancreatic cancer, is upregulated in KRAS-mutant SW48 cells versus isogenic controls." (PMID 28807782, 2017). "Overall, these findings implicate oncogenic KRAS and other genes that are stimulated through KRAS signaling pathways as promising targets for designing effective immunotherapies against pancreatic cancer." (PMID 28587243, 2017). "Mutated KRAS is observed in >90% of pancreatic cancer cases and its downstream mediator, GLI1, is responsible for KRAS–induced pancreatic development/transformation." (PMID 26988754, 2017). "Given the role of COPB2 in apoptosis signaling, as shown by our experiments, we suspect that the simultaneous inhibition of COPB2 and KRAS in pancreatic cancer cells will be more effective than COPB2 silencing alone." (PMID 28415695, 2017). "Other studies have shown that pancreatic cancer cells with oncogenic KRas are dependent on glutamine metabolism for proliferation." (PMID 29212209, 2017). "For example, head and neck tumors carry mutant HRAS, melanomas carry mutant NRAS and pancreatic tumors carry mutant KRAS." (PMID 28815022, 2017). "For instance, mutant KRAS-driven pancreatic cancer cells, which rely on glutamine metabolism to support their growth, can maintain proliferation under glutamine-limiting conditions if supplied with extracellular serum albumin." (PMID 29085336, 2017). "For example, lncRNA-NUTF2P3-001 induced by hypoxia contributes to tumorigenesis of pancreatic cancer through derepressing the miR-3923/KRAS pathway." (PMID 27246976, 2017). "Other studies demonstrated that GLI1 transcription factor acts synergistically with activated KRAS to induce metastatic pancreatic cancer." (PMID 26988754, 2017). "For example, lapatinib plus trametinib in KRAS-MT malignancies is now undergoing a clinical trial (NCT02230553), a phase I/II study with lapatinib plus trametinib in patients with metastatic KRAS-MT colorectal, non-small cell lung and pancreatic cancer." (PMID 27965461, 2017). "Our earlier report described that EVI1 binds to the potential binding site around miR-96 in pancreatic cancer cells and that miR-96 has a potential binding site at 3′-UTR of KRAS in pancreatic cancer cells." (PMID 29245923, 2017).
pancreatic cancer (continued). "Many fundamental cellular signaling cascades were investigated for their crucial involvement in tumor progression in KRAS-independent pancreatic cancer cell lines." (PMID 28895920, 2017). "Further studies are required to explore this mechanistic link in other KRAS-dependent tumour types such as pancreatic cancer to understand the extent of the potential therapeutic opportunity." (PMID 28692044, 2017). "The results of these studies clearly showed that oncogenic KRAS is required for both the initiation and the maintenance of pancreatic cancer in mice." (PMID 29156578, 2017). "In MiaPaCa-2 cells, RHOA and RALA signaling pathways were found essential for KRAS dependent regulation of migration and invasion required for pancreatic cancer metastasis." (PMID 27835861, 2017). "In particular, we observed normalization of expression of KRAS, which is directly related to pancreatic cancer progression, and mevalonate pathway related genes (HMGCS1, MVD, MVK, and PDSS1)." (PMID 29262834, 2017). "In pancreatic cancer, STAT3 was observed during all stages of pancreatic oncogenesis, and inhibition or loss of STAT3 reduced oncogenic KRAS-induced ADM and PanIN formation." (PMID 28738823, 2017). "The main findings of the study were as follows: MALAT1 promotes oncogenesis and enhances KRAS/mitogen-activated protein kinase (MAPK) signalling pathway activation in pancreatic cancer at least in part through a direct interaction with miR-217." (PMID 28701723, 2017). "KRAS is an oncogene that plays a key role in the onset of pancreatic cancer and also plays an essential role in invasive pancreatic cancer." (PMID 28701723, 2017). "Overexpression of KDM2B cooperated with KRAS oncogenic mutants (KRASG12D) to promote pancreatic cancer formation in mice." (PMID 29156578, 2017). "We also found one case that had two KRAS mutations coexisting at similar frequencies (p.G12D VAF=17% and p.G12C VAF=15.4%) something that has been mainly observed in pancreatic cancer with associated PanIN." (PMID 29152076, 2017). "According to these findings, it was concluded that DCLK1, as a potential KRAS effector, functionally contributes to the pathogenesis of pancreatic cancer." (PMID 29156578, 2017). "In this regard, CXCR2 signaling has been shown to regulate KRAS-induced pancreatic cancer growth, whereas IL-8 serves as an autocrine growth factor for malignant mesothelioma maintenance." (PMID 28380429, 2017). "Although the Kirsten rat sarcoma viral oncogene homolog (KRAS) is mutated and activated in > 90% of pancreatic cancers, EGFR expression has also been shown to be essential for KRAS‐driven pancreatic ductal adenocarcinoma." (PMID 28755527, 2017). "In our experiment, Panc1 heterozygous mutant KRASG12D cell line exhibits similar behavior with wild type KRAS pancreatic tumor cells." (PMID 28415695, 2017). "An important role of inflammation in pancreatic tumor development is supported also by the analysis of mouse models based on the transformation of mouse acinar cells by mutant KRAS." (PMID 29156578, 2017).
pancreatic cancer (continued). "Through mutational analyses of human pancreatic neoplasm and establishment of mutant KRAS-driven pancreatic cancer mouse models, researchers have regarded oncogenic KRAS as crucially important for pancreatic carcinogenesis." (PMID 29245923, 2017). "Another recent study showed that oncogenic KRAS activation modifies the glutamine metabolism in pancreatic cancer cells." (PMID 29156578, 2017). "Pancreatic tumor cells depend on KRAS signaling, on evasion of apoptosis and on autophagy to sustain themselves and proliferate." (PMID 28415695, 2017). "The studies carried out at the level of KRAS-induced murine pancreatic cancers have in part clarified this issue." (PMID 29156578, 2017). "Lee and coworkers have recently analyzed in detail the effect of HH signaling on pancreatic cancer progression in three different mouse models of KRas-induced pancreatic cancer." (PMID 29156578, 2017). "In line with this, oncogenic KRAS in PDAC regulates not only cell-autonomous signaling in pancreatic cancer cells, but also leads to production of factors activating PSCs in a cell non-autonomous manner." (PMID 29295482, 2017). "It has been reported that MEK inhibitors, U0126 and PD0325901, abrogate BEZ235-induced (a PI3K/mTOR dual inhibitor) ERK activation in KRAS mutant pancreatic cancer cell lines." (PMID 28574828, 2017). "The study of KRAS-dependent models of pancreatic tumorigenesis was of fundamental importance for the understanding of the cell of origin of pancreatic cancers and for the analysis of the whole process of pancreatic tumor development." (PMID 29156578, 2017). "In present study, the positive correlation between lncRNA-NUTF2P3-001 and KRAS mRNA was further validated in normal pancreas, chronic pancreatitis and pancreatic cancer." (PMID 26755660, 2016). "In pancreatic cancer cell lines, the knockdown of KRAS has been found to lead to the decrease in cell motility and proliferation." (PMID 26904540, 2016). "In human pancreatic cancers, miR-96 down-regulation correlated with an elevation of KRAS expression and KRAS was shown to be a direct target of miR-96." (PMID 26646588, 2016). "Substantial evidence has demonstrated the complexity of oncogenic KRAS signaling in promoting pancreatic cancer." (PMID 27322423, 2016). "The meaningful novel finding of present study is that hypoxia-induced lncRNA-NUTF2P3-001 functions as promoter through depressing the inhibition of miR-3923 on KRAS expression in pancreatic cancer." (PMID 26755660, 2016). "MiR-155 was induced by KRAS oncogenic signal mediated by reactive oxygen species (ROS) generation in pancreatic cancer." (PMID 26646588, 2016). "Both Deltarasin and Deltazinone 1 exhibited an ‘in-cell' measured KD of ∼60 nM for PDEδ, whereas μM concentrations of the inhibitors were required to affect the proliferation of KRas-dependent pancreatic cancer cells." (PMID 27094677, 2016). "It has been shown that GSK-3α promotes oncogenic KRAS function via IKK-NF-κB activity in pancreatic cancer." (PMID 27049759, 2016). "Molecular evidences support the master role of oncogenic KRAS disrupting the metabolic homeostasis via alteration of glucose uptake, glycolytic flux, and glutamine usage in colon and pancreatic tumors that often display very high resilience to chemotherapy." (PMID 27323830, 2016). "With significant and compelling evidence that aberrant KRAS protein function is critical for PDAC growth and maintenance, the Pancreatic Cancer Working Group (NCI) identified targeting KRAS as one of four key priorities for pancreatic cancer research." (PMID 27096871, 2016).
pancreatic cancer (continued). "The largely mutually exclusive frequency of BRAF and RAS mutations supports the notion that RAF is a critical driver in KRAS-mutant pancreatic cancer." (PMID 27096871, 2016). "In colon cancer and pancreatic cancer, detection of KRAS mutant subtypes is extremely useful in predicting the therapeutic efficacy of chemotherapy and in identifying patients with poor prognosis." (PMID 26999437, 2016). "Taken together, our data indicate that recombinant PTD-RBD-VIF interacts with mutant KRAS and induces its ubiquitination and degradation, thereby inhibiting the growth of pancreatic cancer cells in vitro and in vivo." (PMID 27322423, 2016). "We have analyzed the possibilities of pathway targeting using SGS against six different genes, encoding five proteins of the apoptosis pathway (BclxL, Flip, Mcl1L, Xiap, Survivin) and KRas in a panel of human and murine pancreatic cancer cell lines." (PMID 26716649, 2016). "Data from pancreatic cancer patients show a positive correlation between lncRNA-NUTF2P3-001 and KRAS, which is associated with advanced tumor stage and worse prognosis." (PMID 26755660, 2016). "Using this technology, delivery of KRASG12D-specific siRNA clearly dampened KRAS expression and inhibited the in vivo growth of pancreatic tumors in both subcutaneous and orthotopic mouse models." (PMID 27096871, 2016). "RNAi mediated suppression of expression of mutant KRAS in pancreatic cancer cells reduced proliferation, anchorage-independent growth, and tumorigenic growth." (PMID 27096871, 2016). "Intraperitoneally administered recombinant PTD-RBD-VIF potently inhibited the growth of xenografted KRAS-mutant pancreatic cancer cells." (PMID 27322423, 2016). "Several works have shown that YAP can mediate oncogenic KRAS in different human tumour types and even bypass oncogenic KRAS oncogenic addiction in pancreatic cancer." (PMID 27322327, 2016). "This glutamine-dependent pathway has recently shown to support the growth of KRAS-transformed pancreatic cancer cells by increasing the ratio of NADPH/NADP+ which attenuates ROS toxicity though maintenance of reduced glutathione." (PMID 27784287, 2016). "Except for that research reveals that mutation of KRAS is required in the initiation and maintenance of pancreatic cancer, some results further imply that the KRAS overexpression is also valuable to be uncovered for tumorigenesis." (PMID 26755660, 2016). "After downregulating lncRNA-NUTF2P3-001, the proliferation and invasion of pancreatic cancer cell are significantly inhibited both in vitro and vivo, accompanying with decreased KRAS expression." (PMID 26755660, 2016). "SiRNAs against KRAS and the apoptosis associated genes BCLXL, FLIP, MCL1L, SURVIVIN and XIAP were transfected into human and murine pancreatic cancer cell lines." (PMID 26716649, 2016). "We further validated the direct binding of lncRNA-NUTF2P3-001 and 3′UTR of KRAS mRNA with miR-3923 in pancreatic cancer cell by dual luciferase reporter assay." (PMID 26755660, 2016). "Microarray co-assay for lncRNAs and mRNAs demonstrates that lncRNA-NUTF2P3-001 is remarkably overexpressed in pancreatic cancer and chronic pancreatitis tissues, which positively correlates with KRAS mRNA expression." (PMID 26755660, 2016). "Two separate studies in 1994 first described Kirsten rat sarcoma viral oncogene homolog (KRAS) and neuroblastoma RAS viral (v-ras) oncogene homolog (NRAS) mutations in the blood of pancreatic carcinoma and leukemia patients." (PMID 27056366, 2016). "Mutations of KRAS and BRAF are mutually exclusive in pancreatic cancers, which suggest that the activating mutations of these genes can compensate for each other in pancreatic cancer phenotypes." (PMID 25699241, 2015).